MIR2276 (microRNA 2276)
Synonyms: hsa-mir-2276
Gene: MicroRNA gene on chromosome 13 (24,162,416 to 24,162,504, forward strand). Ensembl gene ENSG00000252695.
Homologues: Orthologues: chimpanzee MIR2276 (100% identical).